EZH2 (enhancer of zeste 2 polycomb repressive complex 2 subunit)
Diseases named in the same sentence as EZH2 in open-access papers (continued):
Sharing a sentence is not in itself a finding about the gene and the disease.
infection (continued). "After the 2-hour infection period, followed by washing, the EZH2 selective inhibitor (UNC1999; vs. vehicle) was added to the host cell media containing Gentamycin." (PMID 26964089, 2016). "Exposing naïve host cells to infection-induced CM led to an increase in EZH2 expression in the nucleus." (PMID 26964089, 2016). "In this report, we found a biological response to infection, acute proliferation at 24 hours, which was mediated through activity of an epigenetic writer, EZH2." (PMID 26964089, 2016). "Next, we examined the infection efficiency of EZH2-shRNA lentiviral vector plasmid on CRC cells by treating cells with 0.1 μL, 1 μL or 10 μL lentivirus for transfection." (PMID 27706111, 2016). "CONCLUSION: Uropathogen-induced paracrine factors act epigenetically by altering expression of EZH2, which plays a key role in early host cell proliferative responses to infection." (PMID 26964089, 2016). "The number of PLA signals between vRNP and M1 in EZH2 KD cells decreased to approximately 50% of that in control cells at 6 h post infection." (PMID 27646999, 2016). "The genome-wide recruitment of EZH2 onto the KSHV episome during de novo infection raises the possibility that LANA binds throughout the entire viral genome to recruit EZH2." (PMID 27606464, 2016). "In summary, a critical epigenetic mediator of proliferation, EZH2, is increased in activity and expression by both direct infection and infection-induced paracrine host factors." (PMID 26964089, 2016). "The Western blot showed increase level of β-catenin localized in nucleus was more obvious than that remained in cytosol after infection of Lenti-EZH2." (PMID 27539752, 2016). "FimH+ bacteria increase the level of intracellular infection in turn increasing the EZH2-dependent proliferative response of the host cells." (PMID 26964089, 2016). "We found that infection also increased proliferation at one day post-infection, which was blocked by the EZH2 inhibitor UNC1999." (PMID 26964089, 2016). "In this report, we identified the latent protein LANA to be responsible for recruiting the polycomb proteins onto the viral episome, which shows a widespread binding on the KSHV genome similar to EZH2 during de novo infection." (PMID 27606464, 2016). "We also observed that EZH2 infection reduced ABCA1 mRNA and protein levels in mouse peritoneal macrophages (MPM), aortas, hearts, livers and kidneys of apoE−/− mice." (PMID 27295295, 2016). "Our results show that loss of the LANA gene completely abolished the recruitment of EZH2 onto lytic promoters during infection." (PMID 27606464, 2016). "As expected, CRISPR–Cas9 targeting of EZH2 led to a decrease in EZH2 protein and levels of H3K27me3 in both the G-401 and RD cells at 6 and 9 days post infection." (PMID 26578851, 2015). "As expected, EZH2 expression showed opposite patterns as gga-miR-101-3p on the 10th–11th days of post-infection (equivalent to the 18th and 19th days of egg hatching)." (PMID 26633386, 2015). "Infection of two Ezh2-mutant iPSC clones with lentiviruses expressing two independent shRNAs against Eed promoted a substantial reduction of EED protein levels." (PMID 23468641, 2013). "This supports our data and suggests that at early time points post infection, when viral replication is low, host cells could sufficiently induce an antiviral state through hsa-miR-101-3p and EZH2." (PMID 40981223, 2025). "In addition to these studies, a report has shown that treatment of mammalian cells with EZH2/1 inhibitor induces antiviral state and suppress infection by diverse viral pathogens including ZIKV." (PMID 39946368, 2025). "In summary, our study reports that ZIKV induces expression of SAMe synthase and EZH2 histone methyl transferase that led to increased H3K27me3 methylation at the initial phase of infection possibly to repress the host factors that inhibit virus replication in mosquito cells." (PMID 39946368, 2025).
infection (continued). "Furthermore, at day 5 post-infection, IFNAR1-deficient CD8+ P14 T cells continued to exhibit reduced Ezh2 expression, along with reduced expression of exhaustion-associated molecules, including PD1, TIM3, and TOX, compared to control cells." (PMID 36716323, 2023). "Congenically distinct CD45.1+ control and CD45.1.2+ Ezh2-deficient CD8+ P14 T cells were adoptively cotransferred at a 1:1 ratio into CD45.2+ recipients subsequently infected with LCMV-Cl13 and analyzed by flow cytometry at 5 days post-infection." (PMID 36716323, 2023). "The fold enrichment pathway analysis of the unique proteins in Ezh2 null macrophages indicated an involvement in cell energy status and responses against infection in a single LPS stimulation (upper), while mostly involved in responses to infection in the LPS tolerance group (lower)." (PMID 37239864, 2023). "In addition to the Tcf7 locus, we also measured the methylation status of CpG islands at other TFH lineage related gene loci from both control and Ezh2-/- TFH cells at day 8 after infection." (PMID 36045674, 2022). "By transcription factor analysis, we detected that EZH2 is the key regulator of the NKT subset in CRKP infection conditions, which could mediate mTOR pathway activation." (PMID 36556247, 2022). "Their study found that EZH2 expression in macrophages can limit the activation of inflammatory response subjected to bacterial infection to restrict systemic spread of a localized infection." (PMID 35432300, 2022). "Infection of control animals results in loss of macrophage numbers, a well‐described response, but this is reversed in the absence of EZH2." (PMID 34464475, 2021). "At day 8 after infection, we observed a severe reduction in the phosphorylation of S6 and 4E-BP1 (key targets downstream of mTOR complex 1 [mTORC1]) in TFH and TH1 cells under the condition of EZH2 loss." (PMID 32999031, 2020). "Expression of enhancer of zeste homolog 2 (EZH2) was significantly (P < 0.01) down regulated indicating that genes involved in epigenetic regulation are also differentially expressed in SD patients during the early stage of infection." (PMID 31954402, 2020). "Five days after LM-GP66 infection, EZH2 expression by memory SM CD4 T cells was measured." (PMID 32999031, 2020). "Similarly, we observed greatly diminished numbers of Ezh2-deficient TFH cells, starting from day 4 post-infection, at least partly owing to increased apoptosis." (PMID 30575739, 2018). "Alternatively, the differential posttranslational modifications of LANA acquired during the different phases of de novo infection may be involved in the temporally ordered binding of EZH2." (PMID 27606464, 2016). "Moreover, pharmacologic inhibition of EZH2 activity led to a decrease in infection-induced proliferation at the 24-hour time period." (PMID 26964089, 2016). "Furthermore, shDNMT1 infection in RAW264.7 macrophage-derived foam cells prevented EZH2-induced cholesterol accumulation." (PMID 27295295, 2016). "To further address whether they contributed to the inhibition of lytic replication following de novo infection, we measured lytic gene expressions upon the shRNA-mediated depletion of either EZH2 or RING1B in SLK cells at 72 hpi." (PMID 24367262, 2013). "Consequently, the GSK343-mediated inhibition of EZH2 increased the expression of KSHV lytic genes following de novo infection of various cell types." (PMID 24367262, 2013). "Therefore, future studies could explore whether SAMe synthase-EZH2-mediated H3K27me3 levels are critical for suppressing these responses at different stages of infection." (PMID 39946368, 2025). "A new study showed that Ezh2 is required for differentiation of terminal effector CD8+ T cells but not for memory CD8+ T cell formation, although Ezh2-deficient CD8+ memory T cells are unable to clear infection, suggesting it is required for protective immunity." (PMID 34943965, 2021).
infection (continued). "The mutation of HIF1-2 significantly increased the activation of EZH2 promoter by si-SLC34A2 infection compared with that without any mutation, indicating that HIF1-2 binding site might be involved for SLC34A2-induced EZH2 activation." (PMID 30038060, 2019). "Interestingly, while the gene expression data of acute Ctr infection suggests an initial downregulation of the EZH2 transcription factor and corresponding target genes, long-term culture leads to sustained upregulation of EZH2." (PMID 30886143, 2019). "To examine the cell autonomous effect of Ezh2 on endogenous CD8+ T-cell responses, we co-transferred equal amount of WT (Thy1.1+CD45.2+) and Ezh2−/− (Thy1.1−CD45.2+) splenocytes into lymphoreplete B6/SJL mice (Thy1.1−CD45.1+), followed by infection with vaccinia virus encoding OVA (VVA-OVA)." (PMID 29242551, 2017). "However, both persistent and short-term epigenetic events may occur during UPEC in vitro infection, as the EZH2 and CDKN2A DNA methylation data reveals." (PMID 26964089, 2016). "Thus, we examined the amounts of vRNA and viral mRNA in EZH2 KD cells at 6 h post infection." (PMID 27646999, 2016). "However, our observed increase in WNT5A mRNA during infection was reversed with the inhibitor of EZH2 suggesting that a transcriptional repressor may be regulated by EZH2 in this case." (PMID 26964089, 2016). "Using shRNA or overexpression lentiviral infection in HT22 neuronal cells, the cells were divided into the following groups: sh‐NC + oe‐NC, sh‐circ_0012856 + oe‐NC, and sh‐circ_0012856 + oe‐EZH2." (PMID 40520073, 2025). "Thus, we then assessed whether HRV16 infection in HeLa OHIO could modify EZH2 expression." (PMID 39324790, 2024). "Western blot analysis was used to confirm the infection efficiency of Sh‐HIF‐1α and Sh‐EZH2, as well as the knockdown efficiency of Si‐ALKBH5 and Si‐YTHDF2." (PMID 38344897, 2024). "Congenically distinct CD8+ P14 T cells were transduced with empty vector (EV, CD45.1+) or Ezh2 retroviral constructs (Ezh2 OE, CD45.1.2+), mixed at a 1:1 ratio, and adoptively transferred into CD45.2+ recipients prior to infection with LCMV-Cl13." (PMID 36716323, 2023). "We then infected the control (Ezh2fl/fl) mice and Ezh2-/- mice with LCMV-Armstrong strain, the deletion of EZH2 protein was validated in TFH cells from Ezh2-/- mice at day 8 after infection." (PMID 36045674, 2022). "At days 2.5, 5, 8, and 30 after infection, we sorted the transferred SM CD4 T cells from the spleens of chimeric recipients and analyzed their EZH2 expression levels by confocal microscopy." (PMID 32999031, 2020). "For example, transcription of EZH2 (that expresses the core subunit of PRC2) is up-regulated following TCR co-stimulation, peaks at ~1 day post-infection, and is largely back to basal levels by day 7 post-infection." (PMID 32024856, 2020). "p-SLC34A2 infection increased the expression of HIF-1α and EZH2, indicating that SLC34A2 lies on the upstream of HIF-1α and EZH2." (PMID 30038060, 2019). "To testify the result above and further detect the connection between SLC34A2 and EZH2, we constructed stable sublines of SW480 and HT29 by infection with lenti-si-SLC34A2 or lenti-p-SLC34A2." (PMID 30038060, 2019). "The EZH2 promoter activity was markedly decreased after the infection with si-SLC34A2, suggesting that the activation of the EZH2 promoter is dependent on SLC34A2." (PMID 30038060, 2019). "We then detected Ezh2 Ser21 or Thr487 phosphorylation (pS21-Ezh2 or pT487-Ezh2) status by immunoblotting of sorted polyclonal TFH and TH1 cells elicited by LCMV-Arm infection." (PMID 30575739, 2018). "We retrovirally introduced the WT dual reporters into WT or Ezh2–/– Smarta cells and performed adoptive transfer and LCMV-Arm infection." (PMID 30575739, 2018). "WT or Ezh2–/– Smarta CD4+ T cells were adoptively transferred into congenic recipients, followed by LCMV-Arm infection." (PMID 30575739, 2018).
infection (continued). "Induction of MYC peaked at 19.6-fold 2 days after infection, while induction of ICAM and EZH2 was only 2.1- and 3.6-fold, respectively." (PMID 30487153, 2018). "Since inhibition of EZH2 promotes the activation of numerous immune genes in 3D4/21 AMs, we further examined how it would affect the infection by influenza A virus (IAV), which is a negative-stranded RNA orthomyxovirus." (PMID 36768720, 2023). "PRC2 components EZH2 and SUZ12 are detectable on lytic promoters marked by H3K27me3, and inhibition or knockdown of EZH2 enhances viral gene expression in PEL-derived lines or following de novo infection of SLK cells." (PMID 34452335, 2021). "EZH2 negatively regulates mitochondria-mediated antiviral innate immune responses by blocking the RIG-I/MAVS RNA recognition pathway, and inhibition of EZH2 activates infection-induced IFN-β expression." (PMID 33436557, 2021). "Next, we generated mice lacking EZH2 in the macrophage lineage, for in vivo infection studies, by using the CX3CR1‐cre driver line." (PMID 34464475, 2021). "Also, the infection with lenti-si-SLC34A2 decreased the expression of cyclin D1, which is the target gene of EZH2." (PMID 30038060, 2019). "In addition, Ezh2–/– mice generated few Fas+GL7+ GC B cells and CD138+IgDlo plasma cells in response to infections by VacV and LCMV, and produced little VacV-specific antibody." (PMID 30575739, 2018). "Infection of EBV mildly increased mRNA levels of EZH1 and EZH2 (2.2- and 2.1-fold, respectively)." (PMID 30487153, 2018). "Based in the activation of EZH2, HDAC7 and CREBBP is possible that the changes induced by the infection could be genomically imprinted." (PMID 30248353, 2018). "To determine if p19Arf repression by Ezh2 HMT contributes to the early TFH lineage specification, we analyzed the behavior of adoptively transferred, CTV-labeled Ezh2–/–Arf–/– Smarta CD4+ T cells in response to LCMV-Arm infection." (PMID 30575739, 2018). "Equal number of congenically labeled WT (CD45.2+, Thy1.1+) and Ezh2−/− (CD45.2+, Thy1.2+) Pmel-1 cells were co-injected into non-irradiated B6/SJL mice (CD45.1+, Thy1.2+), followed by infection with vaccinia virus encoding gp100 (VVA-gp100)." (PMID 29242551, 2017). "Decreased expression of EZH2, a histone methyltransferase that deposits H3K27me3 and whose downregulation contributes to upregulation of p16INK4a in senescence, was also observed in both control and SUV420H2-expressing cells upon H-RASG12V infection." (PMID 27457071, 2016). "Surprisingly, EZH2 expression had already been restored to near control levels in the G-401 but not RD cells by 15 or 21 days post-infection, and the proliferation rate in the G-401 cells was restored to approximately control levels." (PMID 26578851, 2015). "We found that, during de novo infection, the binding of RYBP on the viral genome precedes that of EZH2, indicating a sequential recruitment of PcG proteins, where RYBP may recruit PRC1 independently of PRC2 at specific lytic promoters." (PMID 24367262, 2013). "Upon transfer of Ezh2fl/flCd4Cre CD8+ T cell into recipient animals and subsequent immunization with peptide-pulsed dendritic cells, T cells lacking Ezh2 were recovered at lower numbers than control cells and accompanied by reduced IFNγ production, similar to the observations in infection models." (PMID 33117406, 2020). "If EZH2 (or any other epigenetic regulator) is required for establishing silent integration events, then we would expect to see an enhancement of GFP+ cells in the initial infection and a reduction in the number of GFP+ cells after treatment with 1 μM SAHA for 18 h." (PMID 28246360, 2017). "Whether EZH2-dependent reductions of CDKN2A products (p16 and alternate reading frame (ARF)) or other EZH2-dependent mechanisms lead to the proliferative changes in post-infection remains under current investigation." (PMID 26964089, 2016). "This dependency of WNT5A expression on EZH2 during infection has not been previously noted." (PMID 26964089, 2016).
infection (continued). "Repression of the cell cycle regulator p27 was recently shown to require binding of YAP alongside the transcriptional repressors YY1 and EZH2; YAP-mediated recruitment of transcriptional repressors may similarly drive the reduced expression of certain YAP target genes during infection." (PMID 36923592, 2023). "To determine whether the observed, infection-dependent, increase in PcG immunofluorescence could be explained by an overall increase in protein expression, we next performed western blot analysis for the PRC2 proteins EZH2 and SUZ12 as well as the PRC1 proteins BMI1 and RING1B." (PMID 22279536, 2012).